CAPG (capping actin protein, gelsolin like)
Diseases named in the same sentence as CAPG in open-access papers (continued):
Sharing a sentence is not in itself a finding about the gene and the disease.
breast carcinoma (continued). "CREB3L1, CAPG, SPINT1, and GRK3 might be suitable for clinical application in early breast cancer treatment." (PMID 39015775, 2024). "Here, we set out to further characterize the determinants of CapG’s nucleocytoplasmic compartmentalization in the breast cancer cells MDA-MB-231 and resolve changes in CapG shuttling on the single cell level by using fluorescence recovery after photobleaching (FRAP) repeatedly in the same live cell." (PMID 39369027, 2024). "Lastly, CAPG was significantly elevated in VIVA1 cells and has recently been shown to promote breast cancer metastasis via its ability to influence epigenetic modifications in cancer cells and was prognostic for development of metastasis in adjuvant-treated breast cancer patients." (PMID 35318435, 2022). "Importantly, the correlation between CapG level and PI3K/Akt activation is confirmed in breast cancer patient samples and xenograft animal models." (PMID 31660072, 2019). "All this body of evidence strongly suggests that CapG may enhance PI3K/Akt activation, thereby promoting paclitaxel resistance in breast cancer cells." (PMID 31660072, 2019). "Importantly, we validated the positive correlation between CapG expression and levels of Akt activation, as well as PI3K/Akt downstream target gene expression in breast cancer patient samples." (PMID 31660072, 2019). "In conclusion, our data demonstrate that high CapG level is associated with poor RFS and non-pCR in breast cancer patients received PTX-based chemotherapy, which at least in part are owing to increased activation of PI3K/Akt pathway." (PMID 31660072, 2019). "Surprisingly, Akt activation by NES-CapG was significantly decreased compared to that by wild type CapG, suggesting nuclear localization of CapG is critical for activating PI3K/Akt signaling in breast cancer cells." (PMID 31660072, 2019). "Additionally, we previously demonstrated that CAPG could bind to STC-1 promoter region (-451 bp to -75 bp) to activate STC-1 transcription and substantially promote breast cancer metastasis." (PMID 31660072, 2019). "Collectively, these findings strongly indicate that CapG-facilitated enrichment of CBP/p300 at PIK3R1/P50 promoter and increased H3K27 acetylation are essential for induction of PIK3R1/P50 transcription and subsequent PI3K/Akt activation in breast cancer cells." (PMID 31660072, 2019).
glioma (13 papers, 2018 to 2025). A benign or malignant brain and spinal cord tumor that arises from glial cells (astrocytes, oligodendrocytes, ependymal cells). "Furthermore, increased CAPG expression is associated with enhanced immune cell infiltration and poor survival of glioma." (PMID 40438577, 2025). "The expression level of CAPG is higher in glioma tissues than in normal tissues, which is in line with our results." (PMID 39707577, 2024). "CAPG has been reported to be upregulated in various cancer types, such as ovarian cancer, bladder cancer, colorectal cancer, and glioma." (PMID 37354358, 2023). "In previous studies, the expression of CAPG in glioma was high, and increased along with the severity of the disease." (PMID 36566214, 2022). "According to a previous study, CAPG has been demonstrated to be high in glioma, and it is connected with the severity of the cancer as well as patients’ prognosis." (PMID 35332692, 2022). "RT‐qPCR analysis also revealed that linear CAPG was digested while circ_0055412 was resistant to RNase R degradation after glioma cells were treated with RNase R." (PMID 35332692, 2022). "In our study, we discovered that circ_0055412, which was derived from CAPG was dramatically overexpressed in glioma cells and concerned with cisplatin resistance of glioma cells." (PMID 35332692, 2022). "Circ_0055412 contributed to cisplatin resistance of glioma cells via stabilizing CAPG mRNA and modulating Wnt/β‐catenin signaling pathway." (PMID 35332692, 2022). "In glioma cell lines U251 and U87, overexpression of CapG promoted proliferation while CapG knock-down inhibited cell cycle progression and resulted in an increase of G0/G1 cell cycle arrest and a decrease in cells in G phase." (PMID 34948433, 2021). "Besides, increased CAPG expression strongly correlates with the resistance to paclitaxel chemotherapy, and knockdown of the circular RNA circ_0055412 promotes the cisplatin sensitivity of glioma cells through modulation of the CAPG signaling pathway." (PMID 36993823, 2023). "Moreover, upregulation of CAPG partially restored the enhanced cisplatin sensitivity of glioma cells induced by silencing of circ_0055412." (PMID 35332692, 2022). "As reported, CAPG is related to proliferation, metastasis and prognosis in glioma." (PMID 35332692, 2022). "CapG expression also promoted cell migration and invasiveness in glioma cell lines." (PMID 34948433, 2021). "Therefore, in this study, we speculated that circRNAs, which were cyclized from CAPG might also influence glioma progression a." (PMID 35332692, 2022). "Furthermore, a previous study has proved that CAPG contributes to cell proliferation in glioma." (PMID 35332692, 2022). "Importantly, CAPG was identified as a prognosis factor correlated with macrophages in gliomas." (PMID 34858984, 2021). "Each one of the two correlation coefficients manifested that both SPP1 and HMOX1 were consistently co‐expressed with 20 genes in glioma samples, such as VAMP8, RAC2, MSR1, CAPG and FBP1." (PMID 40495644, 2025). "High levels of CapG expression have been found to correlate with lymph node metastasis and advanced TNM stage in various cancer types, including glioma." (PMID 34948433, 2021). "CAPG is involved in macrophage activities such as receptor‐mediated ruffling, phagocytosis, and vesicle transport, with a potential role in TAM polarization in glioma." (PMID 39964147, 2025). "CAPG is expressed at higher levels in glioma tissues than in normal tissues and is significantly associated with prognosis." (PMID 35571123, 2022). "In conclusion, our study elucidates the regulatory mechanism that circ_0055412 regulated EIF4A3/CAPG axis and miR‐330‐3p/NFATC3/Wnt/β‐catenin pathway to promote cisplatin resistance of glioma cells, which might provide the theoretical and practical basis for glioma therapy." (PMID 35332692, 2022). "However, previous studies of CAPG, FANCD2, HMOX1, HSPB1, RRM2, and STEAP3 did not develop any new clinical therapy in glioma." (PMID 36566214, 2022).
colorectal cancer (10 papers, 2011 to 2025). A primary or metastatic malignant neoplasm that affects the colon or rectum. "In a variety of tumors, overexpression of CapG has been demonstrated and recently the association of CapG overexpression and metastasis has been shown in colorectal cancer." (PMID 24804218, 2014). "ACTR3B (actin-related protein 3B) protein expression has been linked to colorectal cancer invasion and proliferation, it is part of a complex with CAPG and CD3D that interacts with several HIV proteins and its expression aids SARS-CoV-2 binding and intracellular processing." (PMID 36299731, 2022). "CAPG suppresses ferroptosis in several cancer types, including pancreatic cancer, colorectal cancer, and HCC." (PMID 40959275, 2025). "In this study, we are the first to address the expression of CapG in human colorectal cancers." (PMID 30155403, 2018). "CAPG promotes the proliferation of colorectal cancer cells by inhibiting ferroptosis, and ferroptosis activation may be a potential therapeutic strategy in hepatocellular carcinoma patients with high CAPG expression." (PMID 39600941, 2024). "Also, CapG message and protein are reported to be up-regulated in colorectal cancer." (PMID 21595958, 2011). "However, the expression and the role of CapG in the human colorectal cancers are still unknown." (PMID 30155403, 2018). "Therefore, we suggest that CapG may play the role of tumor metastasis in human colorectal cancers." (PMID 30155403, 2018).
ovarian carcinoma (10 papers, 2014 to 2025). A malignant neoplasm originating from the surface ovarian epithelium. "Finally, by analyzing a single nucleotide polymorphism localized in exon 10 of the CapG gene, we suggest a novel link between fallopian tube and ovarian carcinomas." (PMID 24804218, 2014). "CapG was described within the German Human Genome project to be overexpressed in breast and ovarian cancer." (PMID 36230711, 2022). "In profiling array analyses, we have formerly shown an increased CapG expression in breast and ovarian cancer." (PMID 24804218, 2014). "In a sample set of 47 ovarian carcinomas and 21 normal tissue samples, CapG overexpression was determined in 38% of all tumor samples (18/47), which was concordant to previous results based on cancer profiling arrays." (PMID 24804218, 2014). "Performing an in silico expression profiling approach for identification of differentially regulated genes in gynecological cancer, CapG has been identified as a putative oncogene overexpressed in breast and ovarian cancer." (PMID 24804218, 2014). "Mean CapG expression levels in tumor specimen and normal tissues differed significantly (P < 0.027) indicating the putative oncogenic function of CapG in ovarian carcinomas." (PMID 24804218, 2014). "Both protein re-distribution scenarios discussed here have been described in gynecologic malignancies and may play a role as prognosticators in these cancers; beta-catenin in endometrial cancer and CapG in breast and ovarian cancer." (PMID 36230711, 2022). "Both proteins may play a role as prognosticators in gynecologic malignancies: beta-catenin in endometrial cancer and CapG in breast and ovarian cancer." (PMID 36230711, 2022).
bladder cancer (8 papers, 2013 to 2026). "Cross-WGCNA and Lasso regression identified SFRP1 and CAPG as key serum proteins linked to bladder cancer and heart failure." (PMID 41701798, 2026). "CapG expression correlated with stage, grade, tumor size and shorter time to recurrence in bladder cancer." (PMID 36230711, 2022). "In bladder cancer and its surrounding tumor microenvironment, CapG was found to be overexpressed compared to normal bladder tissue." (PMID 36230711, 2022). "The TP63, CAPG, SCD, and ZNF419 were found to be significantly upregulated in the bladder cancer tissue samples." (PMID 34386423, 2021). "Moreover, it should be noted that CAPG, another LIN28B-induced matrix protein identified in our study, has been reported as capable of inducing EMT and promoting tumorigenesis in bladder cancer." (PMID 34548635, 2022).
hepatocellular carcinoma (8 papers, 2013 to 2025). A malignant tumor that arises from hepatocytes. "Although it has been reported that CAPG was expressed in the cytoplasm of hepatocellular carcinoma cells and was associated with metastasis and poor prognosis, suggesting its potential as a diagnostic biomarker." (PMID 40982354, 2025). "Furthermore, we explored the anticancer molecular mechanisms and associated signalling pathways of CAPG in hepatocellular carcinoma cells." (PMID 40982354, 2025). "It has been found that GSEA analysis showed CAPG was related to the Nrf2 axis in hepatocellular carcinoma cells." (PMID 40982354, 2025). "Overall, these results indicate that the knockdown of CAPG reverses Dox resistance by inducing ferroptosis through the TGFB1/Nrf2 signalling pathway in hepatocellular carcinoma (HCC) cells." (PMID 40982354, 2025). "It has been shown that CAPG regulates ferroptosis through SLC7A11-mediated GSH synthesis to promote cell proliferation, and the GSH level is decreased after CAPG knockdown in hepatocellular carcinoma." (PMID 39600941, 2024). "These cells express the marker genes CD9 and TREM2, a tumor suppressor in hepatocellular carcinoma, as well as the markers CAPG and GPNMB." (PMID 33332768, 2020). "CapG appears to play an important role in the process of metastasis by promoting the invasiveness of tumour cells as reported in hepatocellular carcinoma." (PMID 24205396, 2013). "Up-regulation of Sema3A expression promoted tumor growth and tumor progression in a hepatocellular carcinoma (HCC) mouse model by enhancement of the expression of CapG, galectin-3, enolase 2 and Epithelial cell adhesion molecule (EpCAM)." (PMID 30696103, 2019). "In hepatocellular carcinoma (HCC), the level of CAPG gene expression showed a strong correlation with both the incidence and prognostic outcomes of HCC." (PMID 38700746, 2025). "Kimura compared hepatocellular carcinoma with and without vascular invasion and found that those with vascular invasion showed markedly up-regulated expression of CapG." (PMID 24205396, 2013).
liver cancer (5 papers, 2015 to 2025). An epithelial or non-epithelial malignant neoplasm that arises from the liver. "The causal relationship between CLTA and CAPG was further observed in the TCGA database of liver cancer and in the in-house cohort of HCC samples, in which their expression was positively correlated." (PMID 37354358, 2023). "In assessing the prognostic value of CAPG in patients with liver cancer, we conducted a time‐dependent ROC curve analysis." (PMID 40982354, 2025). "This was further verified by detecting the expression of CAPG in various liver cancer cell lines, including SNU‐398, HepG2, SNU‐475, and Hep3B (**p < 0.01)." (PMID 40982354, 2025). "Conversely, CAPG, as a ferroptosis downregulated factor, is also upregulated in liver cancer tissues." (PMID 37461802, 2023). "To further explore whether CAPG affects the drug resistance of liver cancer cells to chemotherapy agents, we established Dox‐resistant cell lines HepG2/Dox and Hep3B/Dox." (PMID 40982354, 2025). "Univariate and multivariable regression analysis of CAPG in liver cancer patients." (PMID 40982354, 2025). "Next, we assessed the expression of CAPG in liver cancer tissues and liver cancer cell lines." (PMID 40982354, 2025). "In both the TCGA database of liver cancer and the in-house cohort of HCC, we observed a positive correlation between CLTA and CAPG expression." (PMID 37354358, 2023). "The paired samples of normal tissues and liver cancer tissues in the TCGA database showed that CAPG expression was higher in liver cancer cells compared to normal controls (***p < 0.001)." (PMID 40982354, 2025). "Later, the Venn diagram revealed that SCIN could play a role in liver cancer through ABCC 1, CAPG and PRNP, and the relationship between the three genes and SCIN in liver cancer was verified in GSCA database." (PMID 39108273, 2024).
pancreatic cancer (5 papers, 2009 to 2025). "A correlation of CapG overexpression with cell motility and invasive phenotype of CapG overexpressing breast and pancreatic cancer cell lines was also shown previously." (PMID 24804218, 2014). "CAPG (capping protein (actin filament), gelsolin-like) also contributes in the motility of pancreatic cancer cells." (PMID 20015385, 2009). "In CAPG-overexpressing pancreatic cancer cells, phosphorylation status of other actin-modulating proteins (cofilin, ezrin/radixin) was not significantly altered, suggesting possible involvement of other cellular proteins, such as ornithine aminotransferase and enolase." (PMID 31360146, 2019).
prostate carcinoma (5 papers, 2008 to 2025). A carcinoma that arises from epithelial cells of the prostate gland. "We further tested the ligation frequency between prostate cancer risk locus 2p11.2 and gene CAPG, which was described in our previous study." (PMID 27923366, 2016). "Located in the nucleus and in the cytoplasm, CapG has also been identified as an oncogene, and its overexpression has been associated with poor prognosis and metastasis in several cancers including BC, colorectal, and prostate cancer." (PMID 40149589, 2025). "Our results showing that CAPG can promote GC proliferation are consistent with the results of a study showing that CAPG can promote prostate cancer proliferation." (PMID 38191512, 2024). "To demonstrate the utility of dPCR in quantifying chromatin interactions, we examined two prostate cancer risk loci at 8q24 and 2p11.2 for their interaction target genes MYC and CAPG in LNCaP cell line." (PMID 27923366, 2016). "We tested this assay at two prostate cancer risk regions of 8q24 and 2p11.2 for their interaction target genes MYC and CAPG." (PMID 27923366, 2016). "More recently, they reported that targeting human cancer cells, including breast and prostate cancer cells with an RNAi procedure against CapG, significantly reduced the invasive and motile properties of both cells examined as well as cell aggregation." (PMID 18237446, 2008). "A series of investigations have shown that upregulation of CAPG has been observed in a variety of cancer cells, including breast, pancreatic, lung, liver, and prostate cancers, and CAPG promotes the proliferation, migration, invasion, and metastasis of a wide range of tumor cells." (PMID 38191512, 2024). "The overexpression of CapG in PC3-ML2 compared to PC3-N2 in this study would suggest that CapG can promote invasion and metastasis in prostate cancer." (PMID 23717685, 2013).
COVID-19 (4 papers, 2021 to 2024). A disease caused by infection with severe acute respiratory syndrome coronavirus 2. "Therefore, our result, conforming with previous reports, indicates that simultaneous upregulation of CD40, Flt3L, IL-6, IL-8, and LIF, in association with CAPG and EDIL3, plays a pivotal role in inflammation and recruitment of immune cells in lung tissues of COVID-19 patients." (PMID 36428847, 2022).
endometrial cancer (4 papers, 2022 to 2025). Primary or metastatic malignant neoplasm involving the endometrium (mucous membrane that lines the endometrial cavity). "The low expression of CAPG, AVIL, and SVIL, together with the high expression of GSN, VILL, and FLII, were found to be significantly associated with poor overall survival in endometrial cancer patients." (PMID 39964147, 2025). "We have identified the expression levels of GSN, CAPG, AVIL, SVIL, and FLII as independent survival risk factors in endometrial cancer (EC) patients." (PMID 39964147, 2025). "Among 52 proteins previously identified by the research team, 8 proteins (MMP9, KPYM, LDHA, CADH1, NAMPT, MPO, ENOA and CAPG) achieved the highest accuracy in diagnosing endometrial cancer in CVF." (PMID 39194522, 2024). "In addition, CAPG protein expression was upregulated in endometrial cancer tissues compared to that in normal tissues." (PMID 39600941, 2024). "In addition, the CAPG protein plays an important role in the molecular communication between the embryo and uterine endometrium and in the diagnosis of endometrial cancer." (PMID 39600941, 2024). "For diagnostic biomarker panels, MMP9 and PKM were reliable for discriminating endometrial cancer, while the combination of CTNB1, XPO2, and CAPG revealed higher performance in distinguishing endometrioid from serous endometrial cancer types." (PMID 39194522, 2024). "Based on the previous findings, we propose a hypothesis stating that CAPG and FLII expression may influence the aggressive characteristics exhibited by endometrial cancer cells." (PMID 39964147, 2025). "In vitro studies showed that silencing CAPG and FLII could inhibit proliferation and metastasis in endometrial cancer cell lines." (PMID 39964147, 2025).